UBE2M (ubiquitin conjugating enzyme E2 M)
Description:
Accepts the ubiquitin-like protein NEDD8 from the UBA3-NAE1 E1 complex and catalyzes its covalent attachment to other proteins. The specific interaction with the E3 ubiquitin ligase RBX1, but not RBX2, suggests that the RBX1-UBE2M complex neddylates specific target proteins, such as CUL1, CUL2, CUL3 and CUL4. Involved in cell proliferation.
Synonyms: UBC12; hUbc12; UBC-RS2
Tractability: Small molecule: a structure with a bound ligand is known; a high-quality ligand is known. PROTAC: ubiquitination databases record sites on it; its protein half-life has been measured; a small molecule that binds it is known.
Target class: Enzyme; Transferase
Gene: Protein-coding gene on chromosome 19 (58,555,709 to 58,558,954, reverse strand). Ensembl gene ENSG00000130725.
Subcellular location (Human Protein Atlas): Nucleoplasm; Cytosol; Nuclear bodies; Nucleoli
Pathways (Reactome):
Immune System: Antigen processing: Ubiquitination & Proteasome degradation; Dectin-1 mediated noncanonical NF-kB signaling; NIK-->noncanonical NF-kB signaling
Metabolism of proteins: Neddylation
Signal Transduction: TGF-beta receptor signaling activates SMADs
Gene Ontology:
Molecular function: NEDD8 transferase activity; protein binding; ubiquitin-protein transferase activity; NEDD8 conjugating enzyme activity; ubiquitin-like protein transferase activity
Biological process: protein modification process; protein neddylation; post-translational protein modification; protein modification by small protein conjugation; regulation of postsynapse assembly
Cellular component: nuclear body; nucleolus; nucleoplasm; cytosol; glutamatergic synapse; postsynapse; presynapse
Genetic constraint (gnomAD): Loss-of-function variants: 2 observed, 23.13 expected, observed/expected ratio (o/e) 0.0865, 90% interval 0.034 to 0.27. The upper end of that interval is the gene's LOEUF score, 0.27, which puts it in group 1 of 6, group 1 being the genes least tolerant of losing a copy. Missense variants: 103 observed, 226.12 expected, observed/expected ratio (o/e) 0.46, 90% interval 0.39 to 0.54. Synonymous variants: 97 observed, 89.84 expected, observed/expected ratio (o/e) 1.08, 90% interval 0.92 to 1.28.
Homologues: Orthologues: chimpanzee UBE2M (100% identical), dog UBE2M (100% identical), macaque UBE2M (100% identical), mouse Ube2m (100% identical), rat Chmp2a (96% identical), pig UBE2M (96% identical), guinea pig UBE2M (92% identical), tropical clawed frog ube2m (90% identical), zebrafish UBE2M (87% identical).
Diseases named in the same sentence as UBE2M in open-access papers:
UBE2M is named in the same sentence as 66 diseases in open-access papers, as found by Europe PMC text mining. Sharing a sentence is not in itself a finding about the gene and the disease. The quoted sentences say what the papers report.
breast carcinoma (8 papers, 2017 to 2025). "Collectively, these findings indicate that UBE2M plays a crucial role as an oncogene and that the combination of its inhibitor with fulvestrant presents as an effective treatment strategy for ER+ breast cancer." (PMID 39138151, 2024). "Altogether, these results indicate that silencing of UBE2M suppresses the growth of ER+ breast cancer cells by inducing cell cycle arrest and apoptosis." (PMID 39138151, 2024). "Altogether, our findings reveal that the UBE2M-ERα feedback loop drives breast cancer progression and fulvestrant resistance, suggesting UBE2M as a viable target for endocrine therapy of ER+ breast cancer." (PMID 39138151, 2024). "Given that UBE2M is considered as an oncogene, we validated its potential as a therapeutic target for ERα+ breast cancer." (PMID 39138151, 2024). "Previous studies have demonstrated that the expression of UBE2M is elevated in multiple cancers, including breast cancer, lung cancer and esophageal squamous cell carcinoma." (PMID 39138151, 2024). "Compared with UBE2M silencing or fulvestrant treatment alone, the combination of UBE2M silencing and fulvestrant inhibited tumor growth more significantly, suggesting that UBE2M silencing improved the sensitivity of ER+ breast cancer cells to fulvestrant." (PMID 39138151, 2024). "Functionally, silencing of UBE2M suppressed the growth of breast cancer cells by inducing cell cycle arrest and apoptosis and improved their sensitivity to fulvestrant both in vitro and in vivo." (PMID 39138151, 2024). "The expression patterns of HIF-1α and UBE2M were opposite in these two types of breast cancer cell lines." (PMID 39138151, 2024). "Collectively, these findings in our study demonstrate that the ERα/HIF-1α/UBE2M axis is an oncogenic cascade regulating the development of breast cancer." (PMID 39138151, 2024). "Further investigation is required to explore the involvement of UBE2M in regulating ERα expression and its role in the progression of ERα+ breast cancer, as well as its potential contribution to fulvestrant resistance." (PMID 39138151, 2024). "To explore the role of UBE2M in breast cancer, we first determined its expression in two different subtypes of breast cancer cell lines (ER+: MCF7 and T47D cell lines; ER-: MDA-MB-231 and BT549 cell lines)." (PMID 39138151, 2024). "Altogether, the results indicate that UBE2M silencing increases the sensitivity of ER+ breast cancer cells to fulvestrant by inducing cell cycle arrest and apoptosis, suggesting that UBE2M is a potential driver of fulvestrant resistance." (PMID 39138151, 2024). "We found that UBE2M expression was significantly higher in ER+ breast cancer tissues than in ER-negative (ER-) breast cancer tissues." (PMID 39138151, 2024). "The focus of this study is to investigate the regulatory mechanism of UBE2M expression in ER+ breast cancer, which is mediated by HIF-1α." (PMID 39138151, 2024). "We found that UBE2M expression was remarkably upregulated in ER+ breast cancer cell lines than in ER- breast cancer cell lines." (PMID 39138151, 2024). "It is noteworthy that the prognosis of patients with ER+ breast cancer with high UBE2M expression was poorer than that of patients with low UBE2M expression (OS, p = 2.3e-5; HR = 1.67; RFS, p = 0.0048, HR = 1.19)." (PMID 39138151, 2024). "Silencing of UBE2M suppresses the growth of breast cancer cells by inducing cell cycle arrest and apoptosis and enhances their sensitivity to fulvestrant both in vitro and in vivo." (PMID 39138151, 2024). "It is also crucial to note that in order to assess the effect of UBE2M on the fulvestrant resistance of breast cancer cells, it would be preferable to utilize cell lines derived from fulvestrant-resistant patients." (PMID 39138151, 2024). "Altogether, these findings indicate that UBE2M plays a key role in the progression of ER+ breast cancer." (PMID 39138151, 2024).
breast carcinoma (continued). "Taken together, these findings suggest that a combination therapy involving UBE2M inhibitors and fulvestrant represents an effective therapeutic strategy for treating ER+ breast cancer." (PMID 39138151, 2024). "Additionally, silencing of UBE2M suppressed the growth of breast cancer cells by inducing cell cycle arrest and apoptosis, thereby increasing the sensitivity of cancer cells to fulvestrant both in vitro and in vivo." (PMID 39138151, 2024). "Therefore, targeting UBE2M represents a promising strategy for improving the sensitivity of ER+ breast cancer to endocrine therapy." (PMID 39138151, 2024). "Given that the expression of HIF-1α is high in ER+ breast cancer, we speculated that ERα transcriptionally activates UBE2M through HIF-1α." (PMID 39138151, 2024). "In this study, high expression of UBE2M was found to be associated with a poor prognosis in patients with ER+ breast cancer, but not in those with ER- breast cancer." (PMID 39138151, 2024). "Indeed, we found that silencing of UBE2M reduced the expression of ERα in ER+ breast cancer cell lines." (PMID 39138151, 2024). "As a result, UBE2M may serve as a promising therapeutic target for ER+ breast cancer." (PMID 39138151, 2024). "Kaplan-Meier analysis (Kaplan–Meier plotter [Breast] [kmplot.com]) revealed that patients with breast cancer with higher UBE2M expression had lower OS and RFS rates than those with lower UBE2M expression (OS, p = 0.01, HR = 1.28; RFS, p = 0.0038, HR = 1.16)." (PMID 39138151, 2024). "We also found that neither the SPOP-ASCT2 axis, nor NEDD8 and few neddylation enzymes, including E1 heterodimer NAE1/APPBP1, and UBA3/NAEβ, and two E2s, UBE2M and UBE2F is subjected to regulation by glucose deprivation in breast cancer cells." (PMID 35641493, 2022). "Higher expression of UBE2M indicated a poorer prognosis in patients with ER+ breast cancer but not in those with ER- breast cancer." (PMID 39138151, 2024). "There may be additional potential mechanisms, independent of HIF-1α, that regulate the expression of UBE2M in ER- breast cancer cells." (PMID 39138151, 2024). "However, UBE2M expression was not significantly correlated with prognosis in patients with ER- breast cancer (OS, p = 0.49, HR = 0.89; RFS, p = 0.45, HR = 1.08)." (PMID 39138151, 2024). "Thus, we made a novel observation that ERα transcriptionally activates UBE2M through HIF-1α, suggesting that overexpression of UBE2M may be attributed to the high expression of HIF-1α in ER+ breast cancer." (PMID 39138151, 2024).
hepatocellular carcinoma (7 papers, 2020 to 2025). A malignant tumor that arises from hepatocytes. "UBE2M is involved in the pathogenesis of several diseases, including hepatocellular carcinoma, osteoarthritis, viral infections, and inflammatory diseases, and UBE2M in macrophages plays a crucial role in infection and inflammation." (PMID 39675717, 2025). "This analysis revealed that in hepatocellular carcinoma, the expression of UBE2M was significantly positively correlated with the abundance of Treg, MDSCs, and macrophage M2." (PMID 36690633, 2023). "In hepatocellular carcinoma cells, UBE2M-mediated stabilization of β-catenin, leading to the upregulation of its downstream effectors, known as cyclin D1, promotes the G1/S transition of cells." (PMID 36690633, 2023). "UBE2M was overexpressed in human hepatocellular carcinoma (HCC), such as HepG2, Hep3B, Huh7 cells and PLC/PRF5 cells, but not in normal hepatocytes by Western blotting and tissues array." (PMID 34638383, 2021). "Upregulated ubiquitin-conjugating enzyme E2M (UBE2M) is associated with poor prognosis in malignancies; However, the phenotype and mechanism of action of UBE2M in hepatocellular carcinoma (HCC) remain elusive." (PMID 32012120, 2020). "Herein, the oncogenic role of UBE2M as an E2 NEDD8-conjugating enzyme was explored in hepatocellular carcinoma (HCC) cells, since neddylation plays a critical role in tumorigenesis." (PMID 34638383, 2021). "In hepatocellular carcinoma (HCC), UBE2M can stabilize β-catenin and increase the level of its downstream protein cyclin D1 to promote the progression from G0/G1 phase to S phase." (PMID 33827629, 2021). "The underlying molecular mechanism of UBE2M, so called UBC12, for neddylation cascade remains unclear so far, though UBE2M was reported to be overexpressed in hepatocellular carcinoma (HCC) and H1299 lung cancer." (PMID 34638383, 2021).
lung carcinoma (7 papers, 2017 to 2024). "UBE2M, as an oncogene, has been confirmed to be overexpressed in several tumors, including osteosarcoma, urothelial carcinoma, cholangiocarcinoma, lung cancer, and HCC." (PMID 32012120, 2020). "In lung cancer, knockdown of UBE2M can promote the expression of cyclin-dependent kinase inhibitor 1 (CDKN1A and CDKN1B) and cyclin-associated proteins (such as G2/mitotic-specific cyclin-B1, Cyclin-A2, G1/S-specific cyclin-D3, and Cyclin-dependent kinase 4 homolog) in cell cycle progression." (PMID 33827629, 2021). "In addition, UBE2M acts as a stress-inducible dual gene for neddylation and ubiquitylation and promotes proliferation and migration in HCCs via activation of β catenin and cyclin D1, along with overexpression in several cancers, including HCCs, H1299 lung cancer and osteosarcoma." (PMID 34638383, 2021).
prostate carcinoma (6 papers, 2014 to 2023). A carcinoma that arises from epithelial cells of the prostate gland. "In prostate cancer, UBE2M interacts with NRPL2 and stabilizes its protein, and depletion of NRPL2 or UBE2M significantly increases the niraparib sensitivity of CRPC cells and enhances niraparib-induced tumor growth inhibition." (PMID 35864871, 2022). "GO/KEGG and GSEA analyses were performed to examine the underlying mechanisms of UBE2M and OTUB1 in prostate cancer." (PMID 35864871, 2022). "Taken together, SNHG17 is very likely to influence immune infiltration by upregulating the expression of OTUB1 and UBE2M in prostate cancer." (PMID 35864871, 2022). "Additionally, we observed that the expression of SNHG17, UBE2M, and OTUB1 was significantly correlated with a decreased infiltrating level of immune cells, indicating the immunological role of SNHG17 and its ceRNA regulatory network in prostate cancer." (PMID 35864871, 2022).
Obesity (5 papers, 2023 to 2026). Accumulation of substantial excess body fat. "UBE2M, an essential neddylation E2 enzyme, has been implicated in the pathogenesis of various diseases, including cancers, viral infections, and obesity." (PMID 39675717, 2025). "When mice had Ube2m depleted specifically in macrophages using Lyz-Cre, the development of obesity, insulin resistance, and hepatic steatosis caused by a high-fat diet was significantly mitigated." (PMID 38434245, 2023). "Obesity and other symptoms were significantly alleviated in UBE2M-deficient mice." (PMID 41492274, 2026). "Thus, targeting macrophage UBE2M may have therapeutic value for the treatment of inflammation-induced obesity and associated metabolic diseases." (PMID 38434245, 2023). "Four up-regulated orthologs were primarily associated with lipid metabolism, including glmp (fatty acid uptake and lipogenesis) and ube2m (lipid accumulation and obesity phenotypes)." (PMID 41310639, 2025). "Specifically, the mice with macrophage depletion of Ube2m have alleviated levels of insulin resistance, obesity, and hepatic steatosis induced by a high-fat diet." (PMID 38575611, 2024). "A recent study revealed that Ube2m is essential to obesity-related inflammation induced by macrophages." (PMID 38575611, 2024). "Our collaborative study showed recently that Ube2m plays a critical role in obesity-related inflammation, triggered by macrophages." (PMID 38434245, 2023). "Another study focused on the key role of UBE2M in macrophage-induced obesity-related inflammation." (PMID 41492274, 2026). "In obesity, a noninfectious inflammatory disease, UBE2M contributes to elevated secretion of the inflammatory cytokines IL-1β, IL-6, and TNF, while its absence leads to reduced levels of these cytokines." (PMID 39675717, 2025).
osteosarcoma (5 papers, 2020 to 2024). A usually aggressive malignant bone-forming mesenchymal neoplasm, predominantly affecting adolescents and young adults. "Increasing evidence shows that UBE2M expression is upregulated in many malignancies, including osteosarcoma, urothelial carcinoma, and intrahepatic cholangiocarcinoma, suggesting that UBE2M might be associated with onset and progression of human cancers." (PMID 32012120, 2020). "As acknowledged, the E2 family is essential for the ubiquitination cascade, and UBE2M is a promoter of tumor onset and development, up-regulated in multiple human malignancies, including osteosarcoma, cholangiocarcinoma, and HCC." (PMID 36214767, 2022). "Research has shown that the expression levels of NEDD8-activating enzyme E1 (NAE1) and ubiquitin-conjugating enzyme E2M (UBE2M) are significantly higher in osteosarcoma tissues and cells compared to normal bone tissues and cells, potentially contributing to the onset and progression of osteosarcoma." (PMID 39062505, 2024).
esophageal squamous cell carcinoma (3 papers, 2022 to 2025). Esophageal squamous cell carcinoma (ESCC) is a type of esophageal carcinoma (EC) that can affect any part of the esophagus, but is usually located in the upper or middle third. "In esophageal squamous cell carcinoma cells, UBE2M knockdown triggers apoptosis or senescence in a cell line-dependent manner." (PMID 36690633, 2023). "In lung cancer and esophageal squamous cell carcinoma cells, UBE2M knockdown disturbs cell cycle progression by triggering G2 phase cell cycle arrest, specifically by inhibiting cullins neddylation and upregulating CRL substrates (p21, p27, and Wee1)." (PMID 36690633, 2023).
gastric cancer (3 papers, 2021 to 2024). A primary or metastatic malignant neoplasm involving the stomach. "Micafungin interacts with UBE2M via occupying the catalytic cysteine (Cys111) in UBE2M, thus inhibiting neddylation to accumulate CRLs substrates, resulting in suppression of survival and migration of gastric cancer cells." (PMID 38575611, 2024).
chronic pancreatitis (2 papers, 2021 to 2024). A chronic inflammatory process causing damage and fibrosis of the pancreatic parenchyma. "As we anticipated, the mRNA expression levels of CCL5 and M2 marker CD163 were negatively correlated with the protein level of UBE2M, suggesting the neddylation-associated modulation of macrophages in chronic pancreatitis." (PMID 33723230, 2021). "To this end, we collected pancreatic specimens from patients with clinically confirmed chronic pancreatitis and analyzed the expression of UBE2M by immunohistochemistry, RT-PCR and western blot." (PMID 33723230, 2021). "Compared with normal healthy controls, UBE2M is remarkably decreased in human chronic pancreatitis tissues accompanied by increased CCL5 and CD163 (markers of M2-type macrophages), indicating the important role of NEDDylation in the pathogenesis of chronic pancreatitis." (PMID 39697538, 2024).